MRAS (muscle RAS oncogene homolog)
Diseases named in the same sentence as MRAS in open-access papers:
MRAS is named in the same sentence as 41 diseases in open-access papers, as found by Europe PMC text mining. Sharing a sentence is not in itself a finding about the gene and the disease. The quoted sentences say what the papers report.
Noonan syndrome (6 papers, 2022 to 2026). "Whole-exome sequencing identified a heterozygous MRAS c.203C>T (p.Thr68Ile) mutation affecting a highly conserved residue among RASopathy-associated GTPases, supporting the diagnosis of MRAS-associated Noonan syndrome complicated by infective endocarditis." (PMID 41517739, 2026). "This case expands the genotypic spectrum of Noonan syndrome by supporting MRAS mutations as pathogenic drivers." (PMID 41517739, 2026).
breast carcinoma (4 papers, 2022 to 2025). "The findings of the present study indicate that increased expression of MRAS is linked to decreased expression of ITPK1 in breast cancer, which might lead to underproduction of inositol phosphate 6 (IP6)." (PMID 36077026, 2022). "Considering this information, the possible oncogenic effect of MRAS can be expected to be suppressed by positive coexpression of ITPK1 and reversed in breast cancer." (PMID 36077026, 2022). "The interaction between GNG2 and the muscle RAS oncogene homolog may inhibit the activity of Akt and ERK, thereby suppressing the proliferation of estrogen-dependent breast cancer cells." (PMID 41174058, 2025).
RASopathies (4 papers, 2022 to 2025). "Similarly, the rasopathy-associated Q71R mutation in MRAS, which is expected to inhibit nucleotide hydrolysis and stabilize the active GTP-bound conformation, also resulted in an increase in affinity to the wild-type (WT) SHOC2 LRR domain (8×/3× binary/ternary)." (PMID 35830882, 2022). "Many of the RASopathy-associated genes are in gene families: RAF (BRAF and RAF1), RAS (HRAS, KRAS, MRAS, NRAS, RIT1, and RRAS2), MAP2K (MAP2K1 and MAP2K2), and SOS (SOS1 and SOS2)." (PMID 40496714, 2025). "We next showed that rasopathy-derived SHOC2 GOF mutant M173I results in a twofold increase in MRAS recruitment, which is reverted when the isoleucine is replaced by a glutamic acid." (PMID 35830882, 2022). "Rasopathy-associated mutations SHOC2(M173I) and Q269_H270delinsHY (Q269H/H270Y); MRAS G23V, T68I and Q71R; PP1Cα P50R (corresponding to PP1Cβ P49R); and non-rasopathy SHOC2 LOF mutations D175N and E457K all map to interaction sites." (PMID 35830882, 2022). "Rasopathy mutations of SHOC2, MRAS and PP1C map to subunit interfaces and enhance complex formation, driving RAF dimerization and MAPK flux." (PMID 35830882, 2022). "MRAS, SHOC2 and PP1C are mutated in rasopathies—developmental syndromes caused by aberrant MAPK pathway activation—and SHOC2 itself has emerged as potential target in receptor tyrosine kinase (RTK)–RAS-driven tumours." (PMID 35830882, 2022). "Our structural mapping of disease-relevant rasopathy mutations in SHOC2, MRAS and PP1C, as well as structure–function studies on specific SHOC2 GOF and LOF variants, establish a mechanistic basis for their function." (PMID 35830882, 2022). "We reasoned that rasopathy-associated gain of function (GOF) mutations in SHOC2 and/or MRAS might stabilize the ternary complex and therefore facilitate structural analysis." (PMID 35830882, 2022). "GOF mutations causing rasopathies have been reported on SHOC2, MRAS and PP1Cβ7–10,13,14,19,34,35." (PMID 35830882, 2022). "All three of these RAS proteins have been identified as mutated in RASopathies, along with non-canonical RAS proteins, RIT1, MRAS, RRAS, RRAS2 and RALA." (PMID 35103797, 2022).
coronary artery disease (3 papers, 2013 to 2017). "The SNP rs9818870 (C→U polymorphism) in the MRAS 3′ UTR is associated with a reduced level of M-ras protein in patients with the coronary artery disease (CAD)." (PMID 23896598, 2013). "The genetic variants rs17465637 in MIA3, rs9818870 in MRAS, and rs17228212 in SMAD3 have been associated with coronary artery disease in GWA studies (P<5×10−8), although explaining only a small proportion of the coronary artery disease risk." (PMID 28737528, 2017). "In a preliminary study in heterozygous familial hypercholesterolaemia, we identified a locus linking the early onset of coronary artery disease (CAD) to chromosome 3q.22 and elected to sequence the MRAS gene using the MegaBACE DNA analysis system." (PMID 23738802, 2013).
melanoma (3 papers, 2017 to 2022). A malignant, usually aggressive tumor composed of atypical, neoplastic melanocytes. "MRAS mutation was reported in melanoma (2 of 121 cases) 33 and lung squamous cell carcinoma (3 of 178 cases) 34, but the frequency was less than 2%." (PMID 27891760, 2017). "It would be interesting to check whether there is any correlation between the molecular type of melanoma (mBRAF, mRAS, mNF1, or triple wild type) and TYRP1 expression." (PMID 31624899, 2020). "From other validated targets in this study that have not yet been investigated in melanoma, we would like to point out MRAS, IL1R2, RAB34, LAPTM5, RDH10, and STK32C." (PMID 36139698, 2022).
myocardial infarction (2 papers, 2024 to 2025). Gross necrosis of the myocardium, as a result of interruption of the blood supply to the area, as in coronary thrombosis. "MR analysis identified the causal relationship between foamy cell fate A-related genes (MRAS, MRPS6, and SLC5A3) and the incidence of atherosclerosis and myocardial infarction." (PMID 39766313, 2024).
Obesity (2 papers, 2013 to 2019). Accumulation of substantial excess body fat. "In conclusion, our study suggests that the genomic locus for the MRAS gene confers risk for CAD, obesity and dyslipidaemia." (PMID 23738802, 2013). "Our results demonstrate that the genomic locus for the MRAS gene confers risk for CAD, obesity and dyslipidaemia and point to the possible involvement of other genes or regulatory elements at this locus, rather than changes in the M-Ras protein function, in these events." (PMID 23738802, 2013). "Currently, there is hardly any tangible data available in the literature pertaining to the possible role of the MRAS gene polymorphism in cardiovascular risk traits for CAD, such as obesity, hypertension (HTN), type 2 diabetes mellitus (T2DM) or dyslipidaemic disorders." (PMID 23738802, 2013).
prostate carcinoma (2 papers, 2011 to 2020). A carcinoma that arises from epithelial cells of the prostate gland. "PSMA1, MRAS, LEP, SLC30A3, and RNF7 were found closely related with prostate cancer." (PMID 32528533, 2020).
acute monocytic leukemia (1 paper, 2023). Acute monoblastic leukemia (AML-M5), is one of the most common subtypes of acute myeloid leukemia (AML) that is either comprised of more than 80% of monoblasts (AML-M5a) or 30-80% monoblasts with (pro)monocytic differentiation (AML-M5b). "In contrast, LZTR1 deficiency increased RIT1, KRAS, MRAS, and NRAS expression in fetal liver and acute monocytic leukemia cells." (PMID 37626065, 2023).
atherosclerosis (1 paper, 2024). A disease characterized by the build-up of fatty material and calcium deposition in the arterial wall resulting in partial or complete occlusion of the arterial lumen. "In genetically predicted levels, higher expression of ANXA5, CCDC71L, MED8, MRAS, MRPS6, NTAN1, and SLA5A3 was positively associated with atherosclerosis risk." (PMID 39766313, 2024). "By MR analysis, these DEGs (e.g., MRAS, MRPS6, and SLC5A3) were linked to causal effects with adverse outcomes in atherosclerosis and MI." (PMID 39766313, 2024). "Notably, MRAS, MRPS6, and SLC5A3 were specifically associated with both atherosclerosis and MI risk." (PMID 39766313, 2024).
cardiac hypertrophy (1 paper, 2024). "MRAS induces RAF activation in a classical RAS–dependent manner, and pathogenic mutations in MRAS cause NS with cardiac hypertrophy." (PMID 39352760, 2024).
cerebral infarction (1 paper, 2019). An ischemic condition of the brain, producing a persistent focal neurological deficit in the area of distribution of the cerebral arteries. "In summary, this study provides an evidence that MRAS rs40593 variant may contribute to the risk of increased area of cerebral infarction of IS in Han population." (PMID 31770223, 2019). "Summarily, this study suggested that MRAS rs40593 may contribute to the increased risk of area of cerebral infarction of IS in Han population." (PMID 31770223, 2019).
colorectal tumors (1 paper, 2025). "We discovered that MRAS expression was higher in colorectal tumors compared to normal colorectal tissue." (PMID 39816686, 2025).
COVID-19 (1 paper, 2024). A disease caused by infection with severe acute respiratory syndrome coronavirus 2. "We found novel significant associations with MRAS and WDR89 in gene-based analyses, and constructed a polygenic risk score that explained 1.01% of the variance in severe COVID-19." (PMID 38517939, 2024).
epilepsy (1 paper, 2017). A brain disorder characterized by episodes of abnormally increased neuronal discharge resulting in transient episodes of sensory or motor neurological dysfunction, or psychic dysfunction. "Among them, MRAS turn out to contribute to Ras signaling pathway, which has been confirmed above to be associated with the progression of epilepsy." (PMID 28255556, 2017). "MAPK7 and MRAS are two proliferation-associated genes in our candidate epilepsy associated gene list." (PMID 28255556, 2017). "As for RRAS and MRAS, considering the functional similarity of MRAS and MAPK, the detailed analysis of such genes can be seen below, while the inner relationship between RRAS and epilepsy has also been revealed in mouse model, validating our prediction." (PMID 28255556, 2017).
infective endocarditis (1 paper, 2026). Infective endocarditis (IE) is an infection of the inner lining of the heart chambers (endocardium) and valves. "The contribution of MRAS variants to NS pathogenesis remains poorly characterized, and infective endocarditis (IE) is extremely rare in patients with NS." (PMID 41517739, 2026).
Insulin resistance (1 paper, 2019). Increased resistance towards insulin, that is, diminished effectiveness of insulin in reducing blood glucose levels. "The TUBB2A and MRAS are novel biomarkers for the development of insulin resistance." (PMID 30678306, 2019).
lipid metabolic disorders (1 paper, 2013). "Currently, apart from a study implicating the rs9818870 as a predictor of cardiovascular risk in individuals free of overt heart disease, there is hardly any literature describing the relationship between the MRAS gene or this genomic locus and lipid metabolic disorders." (PMID 23738802, 2013).
pancreatic cancer (1 paper, 2023). "Having observed that treating PANC1 cells with HMT increased the SAH/SAM ratio, we analyzed the localization of MRAS in EGF-stimulated pancreatic cancer cells." (PMID 37996408, 2023).
Stroke (1 paper, 2019). Sudden impairment of blood flow to a part of the brain due to occlusion or rupture of an artery to the brain. "Therefore, it is necessary to investigate genetic effect of the MRAS SNP on stroke susceptibility." (PMID 31770223, 2019).
cancer (20 papers, 2011 to 2026). A tumor composed of atypical neoplastic, often pleomorphic cells that invade other tissues. "However, in stark contrast to RAS, activating mutations in MRAS are rarely found in cancer." (PMID 38053181, 2023). "Dysregulated methylation of WT1, PLEK2, MRAS, and RXRA in the twin with B‐ALL increases cancer susceptibility." (PMID 38970307, 2024). "Abnormal activation of Ras proteins (including RRAS2, MRas, HRas, KRas, and NRas) is the primary stimulus of oncogenes that has an essential role in the main signaling pathway in cancer." (PMID 36251702, 2022). "For instance, among the selected genes were phosphatidylinositol 3-kinases, a gene family involved in multiple cellular functions related to cancer, or MRAS, part of the Ras signalling extensively dysregulated in carcinogenesis." (PMID 21811255, 2011). "Unlike other components of the MAPK pathway, such as KRAS, BRAF, and NRAS, MRAS has not been found to be mutated in human cancers, and perhaps this circumstance has excluded it from being an attractive anticancer target." (PMID 37996408, 2023). "Our analysis of the DepMap data shows that MRAS knockout is well tolerated in cancer cell lines that are strongly dependent on SHOC2 for survival, consistent with the hypothesis that H/K/NRAS may substitute for MRAS in certain contexts." (PMID 35768504, 2022). "In addition to the known cancer genes, we found a putative oncogene, MRAS, and detected R78W substitution in the tumor from patient #4." (PMID 27891760, 2017). "Some tumors exhibit overexpression of MRAS, but no mutations in oncogenic hot spots have been reported in well over 20,000 sequenced cancers (Sanger COSMIC database)." (PMID 26516777, 2015). "In addition, MRAS has also been found involving in RAF activation in certain cancers." (PMID 38970307, 2024). "Interestingly, we found significant co-dependencies of SHOC2 and canonical RAS proteins in cancer cells expressing oncogenic RAS with GTP-activating mutations but no co-dependency to MRAS in this setting." (PMID 35830882, 2022). "Notably, in cancer, canonical RAS proteins but not MRAS are frequently subjected to activating mutations that drive cancer cell survival and proliferation." (PMID 35830882, 2022). "Target gene analysis for these tsRNAs showed them to be cancer-related involving TGF-β and Wnt-signalling-pathways as well as regulating genes AKT1, MRAS, and WNT4." (PMID 35409051, 2022). "This shows that fitness defects caused by SHOC2 inactivation in cancer cell lines are directly associated with the oncogenic activity of H/K/NRAS and are independent of MRAS." (PMID 35768504, 2022). "Thus, features such as EPB41, PSMA1, FGFR3, MRAS, and LEP which were involved in cancer-related pathways and with high PPI degrees (>/ = 10) were considered as PRBs for further analysis." (PMID 32528533, 2020). "Furthermore, by screening through the criteria of the PPI network, cancer-related pathway and TRS modeling, essential features with gene symbols of EPB41, PSMA1, FGFR3, MRAS, LEP, C7orf46, LOC285000, LBP, ZNF35, SLC30A3, LECT2, RNF7, and DYNC1I1 were identified as PRBs for COAD patients." (PMID 32528533, 2020).
tumor (13 papers, 2013 to 2025). "This is the first report of MRAS recurrent mutation in human tumor samples." (PMID 27891760, 2017). "This is the first research to discover MRAS recurrent mutation among human tumor samples." (PMID 27891760, 2017). "Western blot experiments demonstrated significantly higher levels of MRAS protein expression in CRC tumor tissue relative to adjacent normal tissue." (PMID 39816686, 2025). "MRAS is known to play a key role in tumor growth, and it contributes to the activation of several important signalling cascades such as the MAPK and ERK pathways." (PMID 33363029, 2020). "This suggests that MRAS may regulate other signaling pathways involving Rho, Ral or Rap GTPases38,53,54, contributing to tumor cell migration adhesion, endocytosis or invasion." (PMID 39103541, 2024). "Notably, upregulated genes in relapsed SW837 xenograft tumor included MRAS, a homologue of the RAS family of GTPases37, and RasGRP1, a Ras GEF38,39, but not NRAS or HRAS." (PMID 39103541, 2024). "In addition to the role of SHOC2 in tumour settings, gain- and loss-of-function mutations in SHOC2, PP1C and MRAS have been identified in RASopathies with dysregulated MAPK signalling." (PMID 35768504, 2022). "The tumor sample of patient #4 in the discovery set had both MRAS mutation and IGF1R amplification, but the tumor sample of patient #17 with IGF1R amplification in the validation set did not have MRAS mutation." (PMID 27891760, 2017). "Although, primary tumor onset was significantly delayed for mRas/mp5/wtEGFR transformed K5+/K19- cells, these cell lines exhibited similar latency for developing lung metastasis as that of K5+/K19- cells transformed by mRas/mp53/wtErbB2." (PMID 27941987, 2016). "Notably, K5+/K19− cells transformed with mRas/mp53/wtEGFR combination had a significantly longer latency for primary tumor development than other cell lines but more lung metastasis incidence than same cells expressing mRas/mp53/wtErbB2." (PMID 25940703, 2015). "In the F3008 model, when compared to adagrasib treatment alone, treatment with adagrasib plus BI-3406 or cetuximab resulted in a strong downregulation of KRAS and MRAS expression, suggesting durable inhibition of MAPK pathway signaling in residual tumor cells." (PMID 39103541, 2024). "To assess the co-dependency of tumour cell lines on SHOC2 and RAS, we correlated chronos scores for SHOC2 and either MRAS or HRAS, KRAS or NRAS from all 1,061 tumour cell lines in DepMap." (PMID 35768504, 2022). "We evaluated the frequency of MRAS mutation and IGF1R amplification using macrodissected tumor DNA to remove as much as possible of the nontumor tissue." (PMID 27891760, 2017). "Although no RIT1, RRAS2, or MRAS mutations were found in the TCGA BC dataset, one tumor with undetermined ER and HER2 statuses harbored a RAC1 (P69S) mutation, and one TNBC tumor harbored a RHOB (D13Y) mutation." (PMID 28636652, 2017). "Examination of tumor derived cells in vitro showed similar EMT or epithelial morphologies as observed in in vivo tumors, suggesting that different phenotypes conferred by oncogene combination mRas/mp53/mPIK3CA is maintained by both the cell types regardless of microenvironment effect." (PMID 27941987, 2016).
cardiovascular disease (3 papers, 2014 to 2020). "The associations between MRAS polymorphisms and cardiovascular diseases have been a matter of interest in recent years." (PMID 31770223, 2019). "Previous studies have indicated that muscle RAS oncogene homolog (MRAS) gene played an important role in cardiovascular diseases." (PMID 31770223, 2019).
MRAS also shares sentences with these, for which no sentence is quoted: infection (3 papers); diabetes (2); Hypertension (2); Anxiety (1); cardiomyopathy (1); CNS tumors (1); colon cancer (1); dyslipidaemia (1); Fukuyama congenital muscular dystrophy (1); gastric cancer (1); heart disease (1); hyperlipidemia (1); infectious disease (1); ischemic stroke (1); left ventricular hypertrophy (1); LEOPARD syndrome (1); lung squamous cell carcinoma (1); type 2 diabetes mellitus (1).